DDOST (dolichyl-diphosphooligosaccharide--protein glycosyltransferase non-catalytic subunit)
Diseases named in the same sentence as DDOST in open-access papers:
DDOST is named in the same sentence as 57 diseases in open-access papers, as found by Europe PMC text mining. Sharing a sentence is not in itself a finding about the gene and the disease. The quoted sentences say what the papers report.
diabetes (14 papers, 2007 to 2024). "Interestingly, DDOST encodes the AGE-R1 scavenger receptor, a counter regulatory mechanism for advanced glycation end-product induced oxidative stress, with a role in diabetes and ageing, processes clearly relevant to Parkinson's disease." (PMID 17362513, 2007). "When only Group A and Group B were considered, the differences in the expressions of ALOX5, LTB4R, DDOST, and SIRT1 mRNAs were maintained after adjustment for sex, age, diabetes duration, and use of ACEI, ARB, and statin (P < 0.0001 for all genes)." (PMID 32273829, 2020). "In the absence of diabetes, DDOST+/−Pod−Cre mice also had glomerulosclerosis and greater glomerular collagen IV accumulation than wild‐type mice which was not further elevated by diabetes." (PMID 34277994, 2021). "However, with diabetes, DDOST+/−Pod−Cre mice showed a significant accumulation of collagen IV in tubule‐enriched fractions not seen in WT diabetic or non‐diabetic DDOST+/−Pod−Cre mice." (PMID 34277994, 2021).
liver fibrosis (5 papers, 2017 to 2024). "Increasing DDOST expression is associated with impairing liver function and the increase of hepatic fibrosis degrees, hence exacerbating the liver injury." (PMID 35173766, 2021).
breast cancer (4 papers, 2020 to 2024). A primary or metastatic malignant neoplasm involving the breast. "Suppression of ribophorin 1 triggered endoplasmic-reticulum-stress-induced apoptosis in part via upregulation of DDOST in breast cancer." (PMID 38460058, 2024). "SSBP1, TXNRD1, SLC25A5, DDOST, SEH1L, and MCM2 had a significant effect in at least 50% of breast cancer cell lines in the CRISPR-Cas9 and/or RNAi screening data." (PMID 37445737, 2023).
glioma (4 papers, 2022 to 2025). A benign or malignant brain and spinal cord tumor that arises from glial cells (astrocytes, oligodendrocytes, ependymal cells). "Increased expression of DDOST is associated with poor prognosis and immune infiltration in hepatocellular carcinoma, colon cancer, and glioma." (PMID 40963867, 2025). "A recent study compared the expression of DDOST between gliomas and normal brain tissue in the Gene Expression Omnibus (GEO) and Chinese Glioma Genome Atlas (CGGA) databases." (PMID 39223141, 2024). "Results showed that DDOST expression was upregulated in most tumors compared with the corresponding normal tissues including gliomas, and tumors that expressed high levels of DDOST displayed poor prognosis." (PMID 35812432, 2022). "The expression of DDOST was compared between glioma and normal brain tissues in the GEO and Chinese Glioma Genome Atlas (CGGA) databases." (PMID 35812432, 2022). "In this project, we investigated the expression and significance of DDOST in gliomas by bioinformatics and immunohistochemical staining, and preliminarily discussed its impact on the glioma microenvironment." (PMID 35812432, 2022). "Patients with high expression of DDOST had worse prognosis than those with lower levels in gliomas." (PMID 35812432, 2022). "Our results preliminarily suggest that DDOST could serve as a potential target for the treatment of glioma patients, and an independent factor for predicting prognosis in gliomas, but further detailed mechanisms need to be explored in future research." (PMID 35812432, 2022). "Our results showed that DDOST expression was inversely correlated with CD4+ T cells and further illustrated that DDOST may contribute to the immunosuppressive microenvironment of gliomas, which affected the effective of immunotherapy drugs." (PMID 35812432, 2022). "It suggests that DDOST may be a candidate oncogene and an independent factor for predicting poor prognosis in gliomas." (PMID 35812432, 2022).
hepatocellular carcinoma (3 papers, 2024 to 2025). A malignant tumor that arises from hepatocytes. "In hepatocellular carcinoma (HCC), high DDOST expression was found to be associated with poorer overall and disease-specific survival of HCC patients." (PMID 39223141, 2024). "Downregulation of DDOST reduced cell proliferation in hepatocellular carcinoma (HCC)." (PMID 38460058, 2024).
congenital disorder of glycosylation (2 papers, 2019 to 2024). Congenital disorder of glycosylation (CDG) is a fast growing group of inborn errors of metabolism characterized by defective activity of enzymes that participate in glycosylation (modification of proteins and other macromolecules by adding and processing of oligosaccharide side chains). "DDOST is associated with several cancers and congenital disorders of glycosylation." (PMID 39223141, 2024).
steatosis (2 papers, 2017 to 2023). Increased lipid within the cytoplasm of cells. "Whether DDOST+/− mice bypass the development of steatosis and proceed directly into fibrogenic pathways would require further investigation into a high fat diet model." (PMID 28947796, 2017).
cervical (1 paper, 2024). "Furthermore, the mechanism of DDOST-involved cervical oncogenesis needs to be clarified." (PMID 38460058, 2024).
cervical cancer (1 paper, 2024). A primary or metastatic malignant neoplasm involving the cervix. "Cox regression analysis of 33 tumor types showed that the expression of DDOST was significantly associated with prognosis in multiple cancer types, especially cervical cancer." (PMID 38460058, 2024). "Our results demonstrated that DDOST was significantly upregulated in a variety of tumor types and correlated with poor prognosis, including cervical cancer." (PMID 38460058, 2024). "It is required to explore the function of DDOST in cervical cancer cells, including cell proliferation, apoptosis, cell cycle, migration and invasion." (PMID 38460058, 2024). "Quantitative real-time PCR assay and immunohistochemistry (IHC) were performed to validate the role of DDOST in cervical cancer." (PMID 38460058, 2024). "Joint analysis of TCGA and GTEx databases revealed that DDOST was significantly upregulated in 27 of 33 tumor types, including cervical cancer." (PMID 38460058, 2024). "In view of this, our study comprehensively investigated role of DDOST in pan-cancer and cervical cancer." (PMID 38460058, 2024). "DDOST expression in cervical cancer is positively correlated with cancer-promoting immune cell Tregs and negatively correlated with cancer-suppressing immune cells, such as CD8 T cells and NK cells." (PMID 38460058, 2024). "DDOST expression in cervical cancer was positively correlated with cancer-promoting immune cell Tregs and negatively correlated with cancer-suppressing immune cells, such as CD8 T cells and NK cells." (PMID 38460058, 2024). "DDOST was closely associated with RNA splicing via transesterification reactions in GO terms, protein processing in endoplasmic reticulum in KEGG terms, and late phase of HIV life cycle and most cell cycle-related pathways in Reactome terms in cervical cancer." (PMID 38460058, 2024). "Taken together, our findings suggest that DDOST could serve as a prognostic biomarker in cervical cancer as well as in a variety of tumors." (PMID 38460058, 2024). "Cervical cancer patients with high expression of DDOST had worse OS, DSS, DFI, and PFI." (PMID 38460058, 2024). "Therefore, our findings uncovered that DDOST could play an essential role in the tumor microenvironment and tumor immune regulation in cervical cancer, which indicated that DDOST could be a useful biomarker for prognosis and a potential therapeutic target for cancer treatment." (PMID 38460058, 2024). "In cervical cancer, DNA damage repair and EMT related pathways were enriched in DDOST high-expression group." (PMID 38460058, 2024). "Through immunohistochemistry, we found that the protein level of DDOST was higher in tumor tissues than in adjacent non-tumor tissues in 40 cervical cancer patients." (PMID 38460058, 2024).
colitis (1 paper, 2021). Inflammation of the colon. "HE ameliorated colitis in prophylactic in HFD mice and it was, at least partly, due to the restoration of the gut integrity, suppression of inflammation and apoptosis via modulation of colonic Sirt1, RAGE and DDOST signaling." (PMID 34380504, 2021).
colon adenocarcinoma (1 paper, 2021). "The high expression of DDOST in colon adenocarcinoma promotes the proliferation of tumor cells." (PMID 33750478, 2021).
cutaneous squamous cell carcinoma (1 paper, 2024). "DDOST expression was increased and correlated with tumor metastasis in cutaneous squamous cell carcinomas." (PMID 38460058, 2024).
gastric cancer (1 paper, 2024). A primary or metastatic malignant neoplasm involving the stomach. "This is consistent with the finding that a mutation of DDOST causes a general defect in N-linked glycosylation leading to ER stress in gastric cancer cells." (PMID 39223141, 2024).
Nephropathy (1 paper, 2019). A nonspecific term referring to disease or damage of the kidneys. "A SNP array from the FinnDiane population study (n = 2719) inferred that there was an association of the OST48 gene, DDOST (rs2170336), with nephropathy development in individuals with T1D27." (PMID 31541173, 2019).
pan (1 paper, 2022). "In this study, we firstly analyzed the expression and significance of DDOST in pan cancer." (PMID 35812432, 2022).
pancreatic cancer (1 paper, 2024). "In conclusion, our in vitro experiments demonstrated that downregulation of DDOST induces ER stress leading to enhanced ROS formation and apoptosis, as well as reduced proliferation and cell viability in two human pancreatic cancer cell lines." (PMID 39223141, 2024).
peripheral nerve injury (1 paper, 2022). Injury to a peripheral nerve. "Consistent with the expression changes of MOGS, the expressions of many metabolism-associated genes, including DDOST, TUSC3, STT3A, STT3B, RPN1, MAGT1, and GANC, were elevated after peripheral nerve injury." (PMID 35575968, 2022).
soft tissue sarcoma (1 paper, 2025). A malignant neoplasm arising from muscle tissue, adipose tissue, blood vessels, fibrous tissue, or other supportive tissues excluding the bones. "Given its dual roles in glycosylation and immune regulation, DDOST represents a promising candidate for future studies in tumor progression and therapeutic resistance, particularly in soft tissue sarcomas where immune modulation and glycosylation dynamics remain underexplored." (PMID 40963867, 2025).
viral infection (1 paper, 2022). "In addition, DDOST knockdown impaired gradient viral infection (multiplicity of infection (MOI) = 1, 2, 4)-induced phosphorylation of TBK1 and IRF3." (PMID 36449507, 2022). "Collectively, these results suggest that DDOST interacts with MITA at the ER through the TM domain and facilitates MITA trafficking from the ER to perinuclear vesicles upon viral infection." (PMID 36449507, 2022).
tumor (8 papers, 2018 to 2025). "High expression of DDOST was associated with poor prognosis in 11 tumor types." (PMID 35812432, 2022). "This underscores that DDOST not only promotes tumor progression but also serves as a key modulator of the tumor immune microenvironment." (PMID 41413687, 2025). "Through qPCR detection, we found that the expression of DDOST was higher in tumor cell lines than in normal cell lines (P < 0.01)." (PMID 38460058, 2024). "We also analyzed the DDOST expression based on TCGA data and found that DDOST was overexpressed in most tumor types, including CESC." (PMID 38460058, 2024). "Based on these data, we propose that DDOST has a tumor-promoting capacity in PDAC cells by maintaining ER homeostasis and thereby suppressing ROS formation and apoptosis." (PMID 39223141, 2024). "Notably, DDOST knockdown exhibited more potent tumor-suppressive effects and broader biological regulatory functions than STT3A inhibition." (PMID 41413687, 2025). "Inhibiting DDOST could disrupt the glycosylation of critical proteins, thereby impairing tumor growth and enhancing immune recognition." (PMID 41413687, 2025). "High DDOST expression confers poor prognosis of tumor patients." (PMID 38460058, 2024). "Several studies revealed that DDOST might be an oncogene in several tumor types." (PMID 38460058, 2024). "Moreover, we stably knocked down DDOST in MHCC97H cells and established subcutaneous xenograft tumor models using these cells to explore the tumorigenic potential of DDOST in vivo." (PMID 41413687, 2025). "Interestingly, CALU, directly interacting with DDOST and RPN2, is known to be highly expressed in tumor cells and therefore might play a crucial role in cancer progression and the induction of epithelial-to-mesenchymal transition." (PMID 39223141, 2024).
cancer (6 papers, 2019 to 2025). A tumor composed of atypical neoplastic, often pleomorphic cells that invade other tissues. "High expression of DDOST has been linked to poor patient survival and increased malignancy in cancers such as cutaneous squamous cell carcinoma and glioblastoma." (PMID 41413687, 2025). "DDOST has been demonstrated to be upregulated in various cancer, including bladder, breast and colorectal cancer, and to be associated with immune infiltration and poor prognosis in HCC34." (PMID 41413687, 2025). "Our study utilized multiple publicly available data to perform a systematic analysis of the pan-cancer role of DDOST in tumorigenesis." (PMID 38460058, 2024). "All cancer types expressed DDOST, with the highest level of expression in TGCT and the lowest in KICH." (PMID 38460058, 2024). "In summary, DDOST expression has been shown to be relevant in distinct cancers, but little is known about the function of DDOST in the development and progression of PDAC from functional studies or public domain databases." (PMID 39223141, 2024). "On the other hand, the KEGG pathway analysis indicated that cancer-related pathways including cell cycle and DNA replication were positively enriched when DDOST was highly expressed." (PMID 35173766, 2021). "In the end, CCT6A, UTP18, YRDC, RRP12, RFT1, NLE1, and DDOST were essential genes across pan-cancer including COAD cells." (PMID 31867042, 2019). "Evidence has revealed that DDOST plays an important role in cancer development and progression." (PMID 38460058, 2024). "Dependency score analysis by DepMap showed that ACTG1 and RHOQ were less essential across pan-cancer cells including COAD cell lines, and CCT6A, UTP18, YRDC, RRP12, RFT1, NLE1, as well as DDOST were essential across pan-cancer cells including most of COAD cell lines." (PMID 31867042, 2019). "In addition, CCT6A, UTP18, YRDC, RRP12, RFT1, NLE1, as well as DDOST were essential genes across pan-cancer including COAD cells, and ACTG1 and RHOQ were less essential genes in cancer cells." (PMID 31867042, 2019). "Finally, drug sensitivity analysis also suggests that DDOST could be a potential target for anti-cancer therapy." (PMID 38460058, 2024). "Among them, DDOST was highly expressed in 27 cancer types, including CESC, and lowly expressed in 3 cancer types compared with corresponding normal tissues." (PMID 38460058, 2024). "Given the critical role of DDOST in OST activity and N-glycosylation, we hypothesize that DDOST may exert an oncogenic effect in human cancers." (PMID 41413687, 2025). "Dolichyl-diphosphooligosaccharide-protein glycosyltransferase noncatalytic subunit (DDOST), a critical component of oligosaccharyltransferase (OST), is upregulated in multiple cancers, yet its role in HCC is unclear." (PMID 41413687, 2025).
renal disease (4 papers, 2010 to 2023). "We have shown for the first time that globally increasing OST48 through the over-expression of DDOST in a mouse model of diabetes, did not protect against kidney disease." (PMID 31541173, 2019).
autosomal recessive disease (1 paper, 2017). Autosomal recessive form of disease. "Homozygous mutations in DDOST, HADHA or GPR56 genes cause autosomal recessive diseases, thus, the heterozygous variants in these genes carried by the proband like their healthy parents were excluded for the pathogenic mutation." (PMID 29137252, 2017).
DDOST also shares sentences with these, for which no sentence is quoted: type 2 diabetes (6 papers); diabetic nephropathy (4); Hyperglycemia (3); infection (3); Insulin resistance (3); Obesity (3); colon cancer (2); glomerulosclerosis (2); nonalcoholic steatohepatitis (2); Parkinson disease (2); renal fibrosis (2); acute kidney injury (1); adrenal hypoplasia (1); Atrophy (1); autoimmune disease (1); bladder cancer (1); diabetic retinopathy (1); endothelial dysfunction (1); fibrosis (1); Glucose intolerance (1); glycosylation disorders (1); inflammation (1); injury (1); invasive carcinoma (1); kidney (1); kidney injury (1); liver steatosis (1); Lymphadenopathy (1); malaria (1); metabolic syndrome (1).
A further 4 diseases each share a sentence with DDOST in 1 paper.